APOE (apolipoprotein E)
Diseases named in the same sentence as APOE in open-access papers (continued):
Sharing a sentence is not in itself a finding about the gene and the disease.
cognitive decline (continued). "It appears that the APOE ɛ 4 allele lowers the age of onset of the disease and accelerates age-related cognitive decline." (PMID 17431502, 2007). "Modifiable lifestyle factors may influence APOE ε4 fragments levels, potentially mitigating cognitive decline risk." (PMID 39789564, 2025). "Specifically, participants with APOE ε4 (+) and high seizure frequency had the highest risk of CI, which means that the APOE ε4 status may act synergistically with high seizure frequency to exacerbate cognitive decline in older adults with epilepsy." (PMID 40405274, 2025). "In addition, ApoE ɛ4 carriers exhibit an accelerated breakdown of the blood–brain barrier in the hippocampus and medial temporal lobe, which is linked to cognitive decline independently of Aβ and tau pathology." (PMID 40717068, 2025). "Moreover, the interaction between elevated FSH levels and APOE ε4 carrier status contributed to a greater risk of cognitive decline." (PMID 41180813, 2025). "This investigation aimed to elucidate whether the presence of the ApoE ε4 allele contributes to an elevated risk of cognitive decline following a stroke." (PMID 40349252, 2025). "Clarifying this relationship could have important implications for developing targeted interventions and therapies for individuals at higher risk of cognitive decline due to their APOE genotype." (PMID 39824904, 2025). "The top LD-independent variant associated with relative and absolute cognitive decline (N = 103,938) included a missense variant in APOE (rs429358), where each additional copy of the T allele showed protective effects on cognitive decline (e.g., βLOG = −0.03, P = 4.3e-19)." (PMID 40374629, 2025). "While ApoE plays a key role in cholesterol transport and has been implicated in cognitive decline, our findings are insufficient to determine whether ApoE genotype modulates 27-OH metabolism." (PMID 40807100, 2025). "This would allow us to determine whether the APOE ε4 allele has a greater influence on the progression of spatial navigation deficits and the overall rate of cognitive decline over time." (PMID 40456910, 2025). "In addition to imaging, genetic risk factors, particularly the apolipoprotein E ε4 (APOE ε4) allele, have emerged as important contributors to cognitive decline in CSVD populations." (PMID 41153256, 2025). "Exacerbated α-synuclein pathology, accelerated breakdown of the BBB, and faster cognitive decline reported in PD patients with APOE ε4 allele may be early evidence of accelerated neurodegeneration seen in our PD patients." (PMID 40018689, 2025). "Moreover, we uncover a genotype‐ and sex‐specific relationship between LPCAT2 expression, cognitive decline, and pain susceptibility, underscoring the importance of considering both APOE genetic background and sex in AD pathophysiology." (PMID 40959955, 2025). "Extensive research has examined the direct effect of APOE alleles on cognitive decline." (PMID 41042284, 2025). "For instance, the presence of the apolipoprotein E (APOE) ε4 allele has been associated with increased risk of AD and cognitive decline, and its effects may vary by sex." (PMID 40278155, 2025). "For example, recent research suggests that specific diets or supplements may help slow cognitive decline in individuals carrying the APOE ε4 allele." (PMID 40671162, 2025). "Given APOE’s critical role in regulating SELENOP-mediated Se delivery to neurons, these lower Se levels in APOE4 carriers may exacerbate deficiencies in antioxidant defenses, potentially accelerating oxidative damage and cognitive decline." (PMID 39940451, 2025). "Specific patient subgroups, such as those with subclinical cognitive decline or genetic predisposition (eg apolipoprotein E genotype) may be at particularly high risk." (PMID 41282917, 2025). "Genetic predispositions such as APOE ε4 status may also impact treatment outcomes, as it is associated with faster cognitive decline and increased synaptic vulnerability." (PMID 40149759, 2025).
cognitive decline (continued). "Importantly, this neuronal APOE appears central to AD pathogenesis, as its cell-type specific removal prevents both AD-associated cognitive decline and hallmark AD pathology." (PMID 41103078, 2025). "We hypothesize that shorter sleep duration and the APOE ɛ4 allele interacts to disrupt LC functional connectivity, and that this disruption may mediate age-related cognitive decline in CUOA-Aβ+ individuals." (PMID 40994826, 2025). "The apolipoprotein E (APOE) ε4 allele is the most important genetic risk factor for sporadic Alzheimer's disease (AD), yet its mechanisms in AD pathology and cognitive decline remain unclear." (PMID 40642909, 2025). "Furthermore, the burden of white matter abnormalities can also accelerate amyloid accumulation and cognitive decline in those with AD risk factors, such as APOE ε4 genotype." (PMID 41194168, 2025). "Recent studies have highlighted the role of ApoE variants in PD and related cognitive decline." (PMID 39944166, 2025). "Importantly, this study also confirms that covariates, such as the presence of the APOE ε4 allele, have deleterious group level effects on the ability of longitudinal Aβ measures to predict cognitive decline." (PMID 38150745, 2024). "In sum, the enhanced susceptibility to cognitive decline in APOE ε4 carriers may render the brain more receptive to the beneficial effects of social engagement and mindfulness practices, possibly through stress reduction and anti‐inflammatory pathways." (PMID 39392181, 2024). "Furthermore, we developed a Methylation-based Risk Score, which successfully predicted future cognitive decline in an independent validation set, even after accounting for age, sex, APOE ε4, years of education, baseline diagnosis, and baseline MMSE score." (PMID 39649611, 2024). "Together, these results when controlled for amyloid levels in the GM suggest that a decrease in WM myelin is associated with accelerated fibrillar tau accumulation and thus cognitive decline, where the presence of APOE ε4 exacerbate the association between myelin loss and tau accumulation." (PMID 38049659, 2024). "Interestingly, patient studies have shown that GSK3B activity in addition with the APOE-ε4 genotype have been associated with cognitive decline in patients with type 2 diabetes." (PMID 37163077, 2024). "Notably, in these models, APOE-ԑ2 PRS was the most important predictor where higher APOE-ԑ2 risk scores indicated a faster cognitive decline." (PMID 39291164, 2024). "Third, only the APOE gene may be insufficient to fully estimate the genetic risk of cognitive decline, the results of which should be interpreted with caution." (PMID 38225615, 2024). "Additionally, age, APOE ε4 carriage, and diabetes were independently associated with cognitive decline." (PMID 39081396, 2024). "However, effects of APOE on neurodegeneration in cognitively intact individuals, and how these associations evolve with cognitive decline, are unclear." (PMID 38212861, 2024). "The aim of this study is to investigate whether APOE ε4 allele exacerbates the impact of sleep disorder on cognitive decline over time, which may help us understand more about how APOE ε4 and sleep disorder relate to cognitive decline in elderly adults." (PMID 38421124, 2024). "However, the higher risk for Aβ deposition and cognitive decline in female APOE ε4 carriers also appears to be attenuated with advancing age." (PMID 38230720, 2024). "Prospective longitudinal studies are necessary to determine if the intra-individual rates of ODI reductions are (ii) significantly accelerated in APOE ɛ4 carriers and (iii) whether they are associated with cognitive decline." (PMID 38384997, 2024). "Myelin alterations are associated in an APOE ε4 dependent manner with faster tau progression and cognitive decline, and may therefore play a role in the etiology of AD." (PMID 38049659, 2024). "APOE genotype is the most important common genetic determinant of cognitive decline and AD risk." (PMID 36624497, 2023).
cognitive decline (continued). "Additionally, in this latter set of models, APOE-ε4 was independently associated with cognitive decline in all cognitive domains examined, and with larger effect sizes than the AD-PRSw/oAPOE." (PMID 36978190, 2023). "This study also showed that those participants with usual risk factors for cognitive declines, such as apolipoprotein E4 (APOE4), Clinical Dementia Rating (CDR) of 0.5 initial ratings, and abnormal amyloid scans showed greater cognitive decline than the inverse." (PMID 36824566, 2023). "Preservation of memory function and lowered amyloid burden is also observed among APOE ɛ4 carriers, and a decreased risk of cognitive decline in multiple domains was also observed with one meal per week of seafood and long-chain n-3 fatty acids in APOE ɛ4 carriers." (PMID 37509132, 2023). "The APOE genotype is strongly associated with the risk of AD and cognitive decline." (PMID 37680393, 2023). "Moreover, the ApoE genotype has been recognized to modify the risk of AD and cognitive decline through both βA-dependent and βA-independent mechanisms." (PMID 36830944, 2023). "Despite these inconsistencies, the evolving evidence suggests that the APOE ε4 allele could be a risk factor for cognitive decline in neurodegenerative diseases." (PMID 38026513, 2023). "Interestingly, the APOE ε4 isoform gene has been linked to more severe and faster rates of cognitive decline in both PD mouse models and human studies." (PMID 37237983, 2023). "First, we explored whether the presence of the APOE-ε4 allele modifies the association between global VR and cognitive decline, as measured with the PACC." (PMID 36856866, 2023). "The present study aimed to determine whether regional VR of Aβ PET interacts with APOE-ε4 status to predict cognitive decline in a cohort of middle-aged CU participants at high risk of AD." (PMID 36856866, 2023). "The lower risk of cognitive decline in APOE-ε2 and APOE-ε3 carriers suggests a testable hypothesis that older individuals could support the fertility of their descendants." (PMID 37556539, 2023). "However, little is known about the association between physical activity and AD-related cognitive decline according to age and the apolipoprotein E (APOE) ε4 allele (APOE4) as major risk factors." (PMID 37496755, 2023). "In previous studies, multiple risk factors for AD dementia have been reported in SCD including old age, apolipoprotein epsilon 4 (APOE4) allele, concern about cognitive declines, informant’s report of the cognitive decline, existence of neurodegenerations, and amyloid depositions at baseline." (PMID 37550761, 2023). "Cognitive decline is accelerated in E280A carriers who also have an APOE e4 allele." (PMID 37612284, 2023). "Taken together, these studies suggest an interplay between patterns of Aβ and tau spread in determining cognitive decline, which would explain why positivity in regions of late Aβ accumulation is associated with cognitive decline in APOE-ε4 carriers in the present study." (PMID 36856866, 2023). "Few studies have addressed whether anticholinergic (AC) medications for overactive bladder (OAB) cause cognitive decline in individuals with existing cognitive impairment, and whether the APOE ε4 gene increases this risk." (PMID 36506252, 2022). "The only possibility would be to examine the association of APOE-ε4 with cognitive decline." (PMID 36571008, 2022). "Our work supports previous findings, suggesting that the KL-VSHET+ on an APOE ε4 genotype background may modulate Aβ and tau pathology, thereby lowering the intensity of neurodegeneration and incidence of cognitive decline in older controls susceptible to AD." (PMID 35617280, 2022). "Although speculative, it is possible that possession of one copy of the APOE-ε4 allele might result in increased risk of cognitive decline due to altered repair mechanisms following neurotrauma or exacerbate underlying MTBI-related cognitive impairment." (PMID 35250800, 2022).
cognitive decline (continued). "Yet, the ApoE protein is a major cholesterol carrier that supports lipid transport and injury repair in the brain, suggesting deficient lipid transport as a plausible mechanism underlying its role in cognitive decline." (PMID 36501121, 2022). "Polymorphism for the apolipoprotein (ApoE) gene may also increase the effect of tHcy on cognitive decline." (PMID 35351068, 2022). "We speculated that the APOE ε4 allele played an important role in affecting CSF GAP-43 in the pathogenesis of cognitive decline." (PMID 36611808, 2022). "Importantly this includes identifying cognitively normal APOE E3 homozygous individuals who are at most risk for early cognitive decline due to AD." (PMID 36923235, 2022). "If the OCRS is linked to BR, one could speculate that higher OCRS could be associated with a reduced association of APOE-ε4 with cognitive decline due to a better passive tolerance of pathology due to higher neurobiological capital." (PMID 36571008, 2022). "Genetic and epigenetic factors such as apolipoprotein E (ApoE) genotype are known to modify the risk and rate of cognitive decline and might impact the probable CI via gene-environment interactions." (PMID 35329128, 2022). "However, it has been widely accepted that APOE ε4 is the most common genetic risk factor for cognitive decline, and the mechanism underlying ε4 allele effects on cognition is not clear." (PMID 35847686, 2022). "Our objective was to use data from the National Alzheimer’s Coordinating Center (NACC) to determine if OAB AC use is associated with an increase in the risk of cognitive decline, and to examine if APOE ε4 carrier status mediates any cognitive decline observed with OAB AC use." (PMID 36506252, 2022). "Considering this limitation, it can be predicted that if the OCRS mainly acts through CR, higher OCRS should be associated with a reduced association of APOE-ε4 with cognitive decline, since the impact on pathologic changes should be mitigated in individuals with high CR." (PMID 36571008, 2022). "In conclusion, the present findings indicate that APOE-ε4 may contribute to the risk of a lower body mass, particularly FM, among women during the early stage of cognitive decline (i.e., MCI)." (PMID 35276898, 2022). "This study used data from a multicenter prospective cohort study to examine whether the AD-RAI can predict the risk of progression to AD and the level of cognitive decline in patients with MCI with APOE-ε4." (PMID 35572149, 2022). "Although all three of the individuals presented in this manuscript had ApoE ε4 variants (and one was ApoE ε4/4), in this vein, it would be wrong to assume that this means that their cognitive decline is definitively all due to “Alzheimer’s” and evidence of irreversible neurodegeneration." (PMID 35517054, 2022). "The Apolipoprotein E (APOE) gene which is known to be strongly associated with cognitive decline in neurodegenerative diseases, could be a possible candidate." (PMID 36508411, 2022). "Controversy exists about whether the APOE polymorphisms are associated with the rate of cognitive decline in AD patients." (PMID 34127075, 2021). "Analysis of the effect of rs77359862 genotype on the likelihood of conversion using a proportional hazards model adjusting for APOE genotype showed that participants with the mutant allele were 2.66 times as likely to progress to the next stage of cognitive decline (p = 0.023)." (PMID 34785643, 2021). "The results from previous studies have shown that having at least one APOE ε4 allele was associated with faster cognitive decline in cognitively healthy older Taiwanese adults, and PDE7A and MTFR1 genes were associated with the rate of age-related cognitive decline." (PMID 34214049, 2021). "However, APOE ε2 promotes anti-inflammatory and anti-oxidant processes, supports synaptic plasticity, and protects against aging-related cognitive decline, whereas ε4 confers risk for cognitive decline." (PMID 33748669, 2021).
cognitive decline (continued). "Additionally evidence suggests that variants of APOE, protective against risk of AD, also slowed cognitive decline." (PMID 33969178, 2021). "The mechanisms underlying the association between APOE ε4 and cognitive decline remain poorly understood; further research using AD biomarkers may provide insight into these mechanisms." (PMID 33397450, 2021). "Besides age, apolipoprotein E (APOE) is one of the most studied factors associated with cognitive decline." (PMID 33658917, 2021). "The authors reported variation with respect to the factors identified among white and black adults and their associated magnitudes which may be suggestive of gene-environment interactions in the associations between race, APOE, and cognitive decline." (PMID 34193248, 2021). "- Leisure activities reduce the risk of APOE ε4-related cognitive decline." (PMID 34616288, 2021). "Additionally, the rate of cognitive decline was associated with the APOE ε4 allele and SORL1 rs3737529." (PMID 34214049, 2021). "The findings suggest that pulse wave velocity, a non-invasive method to assess arterial wall properties, may be a useful marker of risk for cognitive decline, particularly among individuals who are APOE ε4 carriers or CSF AD biomarke0r-positive." (PMID 34210365, 2021). "In conclusion, we found putative adverse associations between the APOE ε4 allele dosage and cognitive decline in the memory domain among Whites, while among African American women, APOE ε4 allele dosage had a potential protective effect on the domain of attention over time." (PMID 34193248, 2021). "Apolipoprotein E E4 (APOE4) is a risk factor for cognitive decline." (PMID 34780525, 2021). "Additional studies on the ability of cMD to predict cognitive decline and clinical progression in cohorts enriched for AD-risk factors such as APOE-ε4, autosomal dominant mutations, or other more stringent inclusion criteria, would be valuable to confirm our results." (PMID 34588623, 2021). "BBB pericyte injury is a predictor of apolipoprotein E (APOE) ε4-associated cognitive decline." (PMID 34831149, 2021). "However, genes encoding, dystrobrevin-binding protein 1 (DTNBP1), brain-derived neurotrophic factor (BDNF), catechol-O-methyl transferase (COMT) and apolipoprotein E (APOE), have demonstrated a repeated association with cognitive decline." (PMID 34679354, 2021). "Nevertheless, the genetic risk of APOE ε4-related cognitive decline could be partly offset by favorably modifiable factors, such as higher education, more intake of protein-enriched food and choline, and maintaining vascular health." (PMID 34616288, 2021). "We further showed that, when repeating our simulation for separate risk factors associated with disease progression, a positive APOE ε4 status and baseline abnormal total tau levels were associated with steeper cognitive decline at a group level, but also with greater variability in progression." (PMID 34550903, 2021). "Moreover, the rate of cognitive decline was associated with the APOE gene (posterior mean = 0.96, 95% CI: 0.39, 1.57) and SORL1 rs3737529 (posterior mean = 0.58, 95% CI: 0.05, 1.14)." (PMID 34214049, 2021). "The fact that we observed a significant cognitive decline during the follow-up period linked to the effects of APOE-ε4, tobacco smoking, educational attainment and lower wealth, demonstrates our study had the capacity to capture the cognitive decline over time in community-dwelling older adults." (PMID 33293510, 2020). "However, tau-independent BBB dysfunction is also observed with cognitive decline, possibly in relation to APOE ε4-associated BBB impairment in the hippocampus and medial temporal lobes." (PMID 33041998, 2020). "However, a reported APOE-e4-related increase in synapse formation contradicted numerous findings indicating the highest loss of synapses and severity of cognitive decline in APOE-e4 carriers." (PMID 32457598, 2020).